TMEM72 (transmembrane protein 72)
Synonyms: C10orf127; KSP37; bA285G1.3
Tractability: Antibody: its Gene Ontology location is reachable by antibodies, with high confidence; UniProt predicts a signal peptide or a membrane-spanning region. PROTAC: ubiquitination databases record sites on it.
Gene: Protein-coding gene on chromosome 10 (44,911,316 to 44,937,010, forward strand). Ensembl gene ENSG00000187783.
Subcellular location: Cell membrane (Isoform 1); Early endosome membrane; Cytoplasm (Isoform 2); Nucleus
Gene Ontology:
Molecular function: protein binding
Cellular component: cytoplasm; early endosome membrane; nucleus; plasma membrane
Genetic constraint (gnomAD): Loss-of-function variants: 10 observed, 15.7 expected, observed/expected ratio (o/e) 0.64, 90% interval 0.39 to 1.08. The upper end of that interval is the gene's LOEUF score, 1.08, which puts it in group 4 of 6, group 1 being the genes least tolerant of losing a copy. Missense variants: 324 observed, 347.68 expected, observed/expected ratio (o/e) 0.93, 90% interval 0.85 to 1.02. Synonymous variants: 160 observed, 151.2 expected, observed/expected ratio (o/e) 1.06, 90% interval 0.93 to 1.21.
Homologues: Orthologues: chimpanzee TMEM72 (99% identical), macaque TMEM72 (98% identical), dog TMEM72 (87% identical), pig TMEM72 (87% identical), rat Tmem72 (85% identical), mouse Tmem72 (84% identical), rabbit TMEM72 (83% identical), guinea pig TMEM72 (75% identical), tropical clawed frog tmem72 (49% identical), zebrafish tmem72 (36% identical).
Diseases named in the same sentence as TMEM72 in open-access papers:
TMEM72 is named in the same sentence as 8 diseases in open-access papers, as found by Europe PMC text mining. Sharing a sentence is not in itself a finding about the gene and the disease. The quoted sentences say what the papers report.
clear cell renal cell carcinoma (3 papers, 2019 to 2021). "Tmem72 is localized to the mitochondria in human clear cell renal cell carcinoma and is associated with metastasis." (PMID 32117919, 2020). "Previously the associations between TMEM213 and TMEM30B and between TMEM72 and TMEM116 have been described, however, for clear cell renal cell carcinoma." (PMID 34638224, 2021).
glioma (1 paper, 2021). A benign or malignant brain and spinal cord tumor that arises from glial cells (astrocytes, oligodendrocytes, ependymal cells). "High DEGs in grade II gliomas included NNMT, MFAP5, APCDD1L-AS1, C7orf57, HP, SERPINA5, and LTF and some highly downregulated DEGs included ABCA4, PDE6A, GRP, RD3, and TMEM72." (PMID 33948562, 2021).
renal carcinoma (1 paper, 2022). A carcinoma arising from the epithelium of the renal parenchyma or the renal pelvis. "Lastly, the immunohistochemical staining of TMEM72 protein from the HPA database confirmed that TMEM72 was downregulated in renal cancers at the protein level." (PMID 36313638, 2022).
tumor (3 papers, 2015 to 2026). "Future studies should focus on the location and function of TMEM72 protein, which might reveal the underlying mechanisms of tumor progression." (PMID 36313638, 2022). "Limited by the relevant research about TMEM72, it was hard to elucidate the reason for the TMEM72 aberrant expression in tumor cells." (PMID 36313638, 2022). "Removal of each of parameters (i.e., average tumor size in mm and TMEM72 relative expression) from multivariate model lowered the prediction ability of the model, as measured by likelihood ratio test (q < 0.1)." (PMID 26169495, 2015). "TMEM72 overexpression suppressed RCC cell proliferation and tumor growth, whereas its silencing promoted tumor progression." (PMID 42070504, 2026). "It revealed that, together with average tumor size, presence of symptoms, and expression of EPAS1, 2-fold increase in the expression of TMEM72 and TMEM116 decreased the odds of metastases significantly for 22 % and 40 %, respectively." (PMID 26169495, 2015).
TMEM72 also shares sentences with these, for which no sentence is quoted: hepatocellular carcinoma (1 paper); idiopathic interstitial pneumonia (1); neurological disease (1); renal cell carcinoma (1).